ATRX (ATRX chromatin remodeler)
Diseases named in the same sentence as ATRX in open-access papers (continued):
Sharing a sentence is not in itself a finding about the gene and the disease.
astrocytomas (continued). "When stratified into the three groups, loss of ATRX expression (n = 44) retained its role as a negative prognostic marker for malignant progression only among astrocytoma, IDH mutant (p = 0.029)." (PMID 33184319, 2020). "ATRX mutation showed a sensitivity of 72.2%, a specificity of 100%, a positive predictive level of 100%, and an negative predictive level of 89.1% for astrocytoma (p=0.002)." (PMID 30592195, 2019). "Among the 55 astrocytoma IDH wt tumors, all five IDH wt, WHO grade II tumors had mutations that altered telomere function, including four that had TERT promoter (pTERT) mutations, and one that had an ATRX truncating mutation." (PMID 31167453, 2019). "Notably, ATRX and DAXX mutations are almost exclusively associated with H3.3 mutations in paediatric HGG, and ATRX is also mutated in wild type H3.3 adult astrocytoma." (PMID 28284043, 2017). "We found a strikingly high incidence of mutations in the ATRX gene (α thalassemia/mental retardation syndrome X-linked), entirely restricted to IDH-mutant LGGs of astrocytic lineage—astrocytomas and oligoastrocytomas—and mutually exclusive with 1p/19q codeletion." (PMID 23104868, 2012). "In the cohort of the IDH-wt astrocytomas the TERT promoter was mutated in 28 of 41 analyzed patients (68.3%); EGFR amplification was detected in 23 out of 48 analyzed patients (47.9%); and nuclear ATRX loss was detected in 12 (9.6%) patients, while it was retained in 113 (90.4%)." (PMID 41466163, 2025). "However, unlike in human astrocytomas, this mouse model was not engineered to have loss of ATRX expression." (PMID 39324445, 2024). "Notably, decreased ATRX mRNA expression has been found to be indicative of low-grade astrocytoma." (PMID 38898533, 2024). "Finally, we found significant age-dependent associations of ATRX SNV status in astrocytoma but not oligodendroglioma or oligoastrocytoma: ATRX SNVs were associated with improved survival in older patients, but with worse survival in younger patients." (PMID 35017538, 2022). "This study indicates that ALT may be the major telomere maintenance mechanism in IDH1 mutation astrocytoma resulting in histidine substitution at arginine 132 (IDH1R132H) mutated astrocytomas and that IDH1R132H downregulates ATRX expression in vitro resulting in ALT." (PMID 33547950, 2021). "Also, not all ATRX mutations are associated with loss of nuclear staining, so in a tumor with classic astrocytoma histology and a confirmed IDH1 or IDH2 mutation, positive nuclear staining for ATRX does not exclude the diagnosis of astrocytoma." (PMID 30967140, 2019).
astrocytomas (continued). "Importantly, in the group of molecular astrocytoma, patients with ATRX loss had a significantly better outcome than patients without ATRX loss, thus providing evidence that the molecular profile helps to refine the prognosis in malignant glioma patients." (PMID 24559763, 2014). "The clustering of IDH1/ATRX-mutant cases supports the existence of a distinct expression profile, consistent with the biological underpinnings of the IDH-mutant astrocytoma subgroup, as defined in the WHO CNS 2021 classification." (PMID 41517303, 2025). "In grade 2–3 astrocytoma, variations in FGFR4, KIT, NTRK2, and positive immunohistochemistry for ATRX and EGFR showed statistically significant results in univariate survival analysis." (PMID 38970209, 2024). "The study population included 104 adult patients with a histologically confirmed supratentorial WHO grade 2 astrocytoma (IDH1/2 mutant, ATRX mutant, n = 70) or oligodendroglioma (IDH1/2 mutant, 1p19q codeleted, n = 34)." (PMID 35356212, 2022). "ATRX immunostaining tends to be positive for oligodendrogliomas and is useful to distinguish between IDH Mut oligodendrogliomas and astrocytomas." (PMID 34020723, 2021). "Expression of IDH1 R132H assessed by IF in the astrocytomas was too weak to perform reliable double pSTAT3/IDH1 R132H stainings so, as an alternative, pSTAT3/ATRX stainings were done." (PMID 32218467, 2020). "We present a case of IDH-mutant astrocytoma with a somewhat atypical molecular presentation, including a previously uncharacterized IDH2 mutation, retained ATRX expression, and lack of MGMT promoter hypermethylation." (PMID 41736408, 2026). "Only four tumors retained positivity for anti-ATRX, and the diagnosis of astrocytoma in these cases was confirmed by 1p/19q non-codeletion via fluorescence in situ hybridization." (PMID 39636550, 2025). "Moreover, higher ITSS levels correlate with an elevated Ki-67 labeling index (Ki-67 LI) and ATRX gene wild-type status, both of which are markers of poorer prognosis in IDH-mutant astrocytomas." (PMID 40052095, 2025). "For IDH-mutant astrocytomas without a primitive neuronal component, the usual TMM alteration is a loss of function event on the ATRX gene." (PMID 39899075, 2025). "For example, in the cluster of IDH1/2-mutant astrocytoma without ATRX alteration (cluster 6), while median overall survival was nearly 12 years, more than a quarter of tumors were grade 4." (PMID 39584448, 2025).
astrocytomas (continued). "ATRX loss was indicative of non-amplified EGFR, largely in astrocytoma." (PMID 37665980, 2023). "Infratentorial IDH-mutant astrocytomas are less common, however, they have been found to frequently possess non-canonical IDH mutations and usually lack ATRX mutations, suggesting they may represent a unique subset of IDH-mutant astrocytomas." (PMID 37239289, 2023). "We explored the relationship between the IFN-γ -associated gene scoring model and various clinicopathological factors, and found that patients with advanced tumor grade, Astrocytoma, wild-type IDH1, 1P/19Q non-co-deletion, and wild-type ATRX had significantly higher risk scores (p < 0.05)." (PMID 36712869, 2022). "Furthermore, sequencing of three subependymal giant cell astrocytoma (SEGA)-like astrocytomas in NF1 mutant patients with ALT and intact ATRX have revealed genetic alterations in RECQL4, Fanconi anemia complementation group genes (FANCD2, FANCF, and FANCG), and SMARCAL1." (PMID 34069193, 2021). "A significantly higher frequency of ATRX loss was also observed in GC compared with patients without GC, both in IDH-mutant astrocytomas (P = 0.020, not shown) and IDH-wildtype glioblastomas (P = 0.018), suggesting that ATRX loss may also play a unique role in the manifestation of GC." (PMID 39127694, 2024).
glioblastoma (144 papers, 2012 to 2026). The most malignant astrocytic tumor (WHO grade IV). "Further molecular testing revealed features more consistent with glioblastoma: multiple large chromosomal aberrations, including loss of the entire chromosome 1 and 2q; a missense mutation in ATRX; and amplification of MYCN, MET, and CDK4." (PMID 41596318, 2026). "ATRX is a chromatin remodelling factor that is frequently altered in glioblastoma patients and is associated with maintenance defects." (PMID 40282990, 2025). "ATRX (alpha-thalassemia/mental retardation syndrome X-linked) mutations are often found in secondary glioblastomas and are typically linked with alternative lengthening of telomeres (ALT), a telomerase-independent mechanism for maintaining telomere length." (PMID 39767571, 2024). "Retained ATRX is confirmed to be associated with IDH wildtype in glioblastoma, as well as with the presence of IDH-mutants, TERT mutants and 1p/19q codeletions, in oligodendroglioma." (PMID 37665980, 2023). "ATRX gene mutation or ATRX protein deficiency by immunohistochemistry in an IDH-wildtype glioblastoma should also raise suspicion diagnostically for this subtype." (PMID 38079020, 2023). "Recently, somatic mutations in the ATRX gene have been detected in osteosarcoma, pancreatic neuroendocrine tumors (PanNets), glioblastoma multiforme, diffuse intrinsic pontine glioma (DIPG), and neuroblastoma (NB)." (PMID 35444965, 2022). "ATRX mutation is mutually exclusive with the 1p/19q co-deletion; thus, this mutation is characteristic of secondary glioblastoma from an astrocytic descent." (PMID 35806478, 2022). "Another recently described signalling pathway in glioblastoma is the telomerase-related senescence escape pathways through mutation of the ATRX (alpha thalassemia/mental retardation syndrome X-linked) gene or TERT (telomerase reverse transcriptase) promoter." (PMID 34683160, 2021). "In this work, we demonstrate that inactivation of KDM4B, through H3.3G34R or IDH1/2 mutations, acts in tandem with ATRX mutations to promote ALT in glioblastomas." (PMID 33972520, 2021). "In conclusion, we provide evidence that inactivation of KDM4B is a critical factor in activating the ALT pathway in ATRX-mutated glioblastomas." (PMID 33972520, 2021). "We have identified KDM4B as a novel factor involved in ALT in ATRX-mutated glioblastomas, and KDM4B can be inactivated either through H3.3G34R or IDH1R132H." (PMID 33972520, 2021). "To identify these factors, we searched public cancer genome databases for mutations that segregated with ATRX inactivation in glioblastoma multiforme (GBM), where ALT is particularly prevalent." (PMID 33972520, 2021). "In recent years, with whole-genome sequencings in cancer, ATRX mutations/losses have been detected in a variety of cancers, such as PanNETs, Glioblastoma multiforme (GBM), neuroblastoma, adrenocortical tumor, pediatric osteosarcoma, angiosarcomas, and Gliomas." (PMID 35087762, 2021).
glioblastoma (continued). "The ATRX mutation is considered ahallmark of astrocytic tumors; it is closely associated with the IDHmutation in diffuse astrocytomas and secondary glioblastomas." (PMID 31413876, 2019). "In contrast, in IDH-WT glioblastomas ATRX mutations were a favorable prognostic factor, while TERTpMUT are a negative prognostic factor." (PMID 30279357, 2018). "IDH wild-type and IDH mutant glioblastoma display different characteristics, and IDH mutant glioblastoma will also exhibit 71% of ATRX gene mutations." (PMID 29200599, 2017). "In 2012, mutations in the H3F3A and ATRX genes were detected in 30 – 40% of pediatric glioblastomas and in a smaller percentage of adult glioblastomas." (PMID 24559763, 2014). "Somatic mutations in ATRX were identified in patients with α-thalassemia myelodysplasia (ATMDS) but recent work has shown that ATRX is also mutated in pancreatic neuroendocrine tumours and glioblastomas." (PMID 23284920, 2012). "However, the morphological features combined with loss of ATRX expression ultimately led to a final diagnosis of glioblastoma, IDH-wildtype." (PMID 41596318, 2026). "Interestingly, ATRX mutations are associated with Ras pathway mutations in glioblastoma; ATRX mutation is associated with a better prognosis." (PMID 40564017, 2025). "Although ATRX is common in low-grade glioma, it is much less commonly found in glioblastoma patients (about 10%) and has been associated with improvement in survival and increased radiosensitivity in patients with glioblastoma." (PMID 39796751, 2025). "Interestingly, our results suggest that mutations that abolish ATP hydrolysis activity of ATRX predominantly impact glycolysis, a metabolic pathway that drives growth and malignancy in solid tumors including neuro- and glioblastomas." (PMID 35998910, 2022). "In addition to ATRX syndrome, ATRX mutations occur frequently in neuroblastoma, glioblastoma, and osteosarcoma cancers." (PMID 35998910, 2022). "Alternatively, mutation and loss of ATRX, which is consistently found in G34 mutant glioblastoma, could contribute to hypo-methylation at highly repeated sequences such as rDNA." (PMID 36412091, 2022). "We identify H3.3G34R and IDH1/2 mutations as two such factors in ATRX-mutated glioblastomas." (PMID 33972520, 2021). "By searching public cancer genome databases, we identified H3.3G34R and IDH1R132H as potential mutations which may collaborate with ATRX to induce ALT in glioblastomas affecting younger age groups." (PMID 33972520, 2021). "Finally, a recent study shows that ATRX deficiency promotes G-quadruplexes stabilization and DNA damage in glioblastoma cells." (PMID 31180492, 2019). "On the other hand, mutations in ATRX are strongly associated with pediatric glioblastoma." (PMID 31180492, 2019).